RNF121 (ring finger protein 121)
Description:
E3 ubiquitin ligase which accepts ubiquitin and transfers it to substrates thereby promoting their degradation by the endoplasmic reticulum-associated degradation (ERAD) pathway which is a pathway involved in ubiquitin-dependent degradation of misfolded endoplasmic reticulum proteins (By similarity). May regulate the unfolded protein response to reduce endoplasmic reticulum stress (By similarity).
Synonyms: FLJ11099
Tractability: Antibody: UniProt predicts a signal peptide or a membrane-spanning region. PROTAC: its protein half-life has been measured.
Gene: Protein-coding gene on chromosome 11 (71,929,018 to 71,997,597, forward strand). Ensembl gene ENSG00000137522.
Subcellular location: Endoplasmic reticulum membrane
Subcellular location (Human Protein Atlas): Golgi apparatus; Nucleoplasm; Vesicles
Gene Ontology:
Molecular function: ubiquitin protein ligase activity; metal ion binding
Biological process: ERAD pathway; protein ubiquitination
Cellular component: endoplasmic reticulum membrane; Golgi membrane
Genetic constraint (gnomAD): Loss-of-function variants: 14 observed, 34 expected, observed/expected ratio (o/e) 0.41, 90% interval 0.27 to 0.64. The upper end of that interval is the gene's LOEUF score, 0.64, which puts it in group 2 of 6, group 1 being the genes least tolerant of losing a copy. Missense variants: 298 observed, 356.53 expected, observed/expected ratio (o/e) 0.84, 90% interval 0.76 to 0.92. Synonymous variants: 125 observed, 124.99 expected, observed/expected ratio (o/e) 1, 90% interval 0.86 to 1.16.
Homologues: Orthologues: chimpanzee RNF121 (100% identical), macaque RNF121 (99% identical), dog RNF121 (99% identical), mouse Rnf121 (98% identical), rat Rnf121 (98% identical), guinea pig RNF121 (97% identical), pig RNF121 (94% identical), rabbit RNF121 (94% identical), tropical clawed frog rnf121 (91% identical), zebrafish rnf121 (80% identical), Drosophila melanogaster CG15814 (56% identical), Caenorhabditis elegans rnf-121 (51% identical). Paralogues in human: RNF175 (69% identical).
Diseases named in the same sentence as RNF121 in open-access papers:
RNF121 is named in the same sentence as 15 diseases in open-access papers, as found by Europe PMC text mining. Sharing a sentence is not in itself a finding about the gene and the disease. The quoted sentences say what the papers report.
lung carcinoma (2 papers, 2018 to 2020). "Moreover, lung cancer patients with high expression of circRNA-100876 (encoded by RNF121) had shorter survival times compare to lung cancer patients with lower expression." (PMID 32300345, 2020).
breast carcinoma (1 paper, 2014). "RNF121 is part of a chromosomal band (11q13) that may contain a high penetrance gene for breast cancer." (PMID 25388546, 2014).
co-infection (1 paper, 2019). "Recombinant AAV transduction is partially rescued by overexpressing RNF121, but not by co-infection with helper Adenovirus." (PMID 31386698, 2019).
colorectal cancer (1 paper, 2021). A primary or metastatic malignant neoplasm that affects the colon or rectum. "This study was designed to reveal the mechanism of circ-ring finger protein 121 (circ-RNF121) in colorectal cancer (CRC)." (PMID 34742305, 2021).
glioblastoma (1 paper, 2019). The most malignant astrocytic tumor (WHO grade IV). "This phenotype was recapitulated in the HEK293 human embryonic kidney and U87 glioblastoma cell lines, which were chosen in order to interrogate the consequences of RNF121 KO in divergent cell lines derived from other tissues." (PMID 31386698, 2019).
renal cell carcinoma (1 paper, 2021). "Further research revealed that overexpressed RNF121 inhibited the growth and invasion of human renal cell carcinoma cells by activating NF-κB signaling pathways." (PMID 35223862, 2021). "In another study, RNF121 levels were found decreased in renal cell carcinoma samples than adjacent normal tissues." (PMID 35223862, 2021).
viral infection (1 paper, 2019). "Ingenuity Pathway Analysis of significant hits enriched in RNF121 KO capsids revealed augmented representation of genes associated with RNA processes (green), translation (blue), viral infection (lime), and DNA damage (purple), with some overlap of hits involved in these processes." (PMID 31386698, 2019).
cancer (5 papers, 2021 to 2024). A tumor composed of atypical neoplastic, often pleomorphic cells that invade other tissues. "For example, four exosomal circRNAs, circPDK1, circ-RNF121, circ_0072083, and circFNDC3B promote glycolysis in cancer cells by acting as molecular sponges for miRNAs and thus contribute to cancer progression." (PMID 37599427, 2023). "In particular, circ-ring finger protein 121 (circ-RNF121), only named as circ_100876, regulates the development of digestive system-related cancers." (PMID 34742305, 2021). "Hsa_circ_0023404, originating from ring finger protein 121 (RNF121), acts as an oncogene in various cancers, including CRC, CC, and NSCLC." (PMID 38671354, 2024).
tumor (3 papers, 2021 to 2023). "For instance, circ-RNF121 regulates tumor progression along with glucose metabolism via the CRC miR-1224-5p/FOXM1 axis." (PMID 36276867, 2022). "Results showed that tumor volume and weight were dramatically smaller or lighter in sh-circ-RNF121 transfection group than in sh-NC transfection group." (PMID 34742305, 2021). "The impacts of circ-RNF121 silencing on tumor formation in vivo were disclosed by in vivo tumor formation assay." (PMID 34742305, 2021). "Previous researches have revealed the importance of circ-RNF121 in tumor development." (PMID 34742305, 2021). "The effects of circ-RNF121 silencing on tumor growth in vivo were further disclosed." (PMID 34742305, 2021). "In addition, our data explained that circ-RNF121 knockdown restrained tumor growth in vivo." (PMID 34742305, 2021). "Thus, circ-RNF121 regulates tumor glucose metabolism and progression via miR-1224-5p/FOXM1 axis in tumor tissues." (PMID 37208722, 2023). "Furthermore, we found that decreasing circ-RNF121 expression led to significant expression inhibition of HK2 and PKM2 in the forming tumor tissues, two key glycolytic enzymes." (PMID 34742305, 2021).
infection (1 paper, 2019). The state of being infected such as from the introduction of a foreign agent such as serum, vaccine, antigenic substance or organism. "Approximately 80% of AAV GFP mRNA was present at 30hrs post-infection in both Scr and RNF121 KO cells indicating that reduced stability of the AAV mRNA transcript cannot explain the large decrease in steady-state AAV mRNA levels seen in RNF121 KO cells." (PMID 31386698, 2019).
RNF121 also shares sentences with these, for which no sentence is quoted: age-related macular degeneration (1 paper); diabetes nephropathy (1); diabetic retinopathy (1); osteoarthritis (1); renal carcinoma (1).